Y_RNA (Y RNA )
Gene: Miscellaneous RNA gene on chromosome 3 (48,288,587 to 48,288,694, forward strand). Ensembl gene ENSG00000199476.
Homologues: Orthologues: chimpanzee Y_RNA (100% identical), macaque Y_RNA (94% identical). Paralogues in human: Y_RNA (88% identical), Y_RNA (86% identical), RNY1P5 (85% identical), Y_RNA (85% identical), RNY1P6 (84% identical), Y_RNA (84% identical), Y_RNA (83% identical), RNY1P14 (82% identical), Y_RNA (82% identical), Y_RNA (81% identical), RNY1 (81% identical), RNY1P1 (81% identical), and 95 more.